SPHKAP (SPHK1 interactor, AKAP domain containing)
Description:
Anchoring protein that binds preferentially to the type I regulatory subunit of c-AMP-dependent protein kinase (PKA type I) and targets it to distinct subcellular compartments. May act as a converging factor linking cAMP and sphingosine signaling pathways. Plays a regulatory role in the modulation of SPHK1.
Synonyms: SKIP
Tractability: PROTAC: ubiquitination databases record sites on it; its protein half-life has been measured.
Gene: Protein-coding gene on chromosome 2 (227,979,955 to 228,181,687, reverse strand). Ensembl gene ENSG00000153820.
Subcellular location: Cytoplasm
Gene Ontology:
Molecular function: protein binding; protein kinase A binding
Cellular component: cytoplasm; mitochondrion
Genetic constraint (gnomAD): Loss-of-function variants: 67 observed, 140.18 expected, observed/expected ratio (o/e) 0.48, 90% interval 0.39 to 0.59. The upper end of that interval is the gene's LOEUF score, 0.59, which puts it in group 2 of 6, group 1 being the genes least tolerant of losing a copy. Missense variants: 2,093 observed, 2,164.2 expected, observed/expected ratio (o/e) 0.97, 90% interval 0.93 to 1. Synonymous variants: 812 observed, 826.38 expected, observed/expected ratio (o/e) 0.98, 90% interval 0.93 to 1.04.
Homologues: Orthologues: chimpanzee SPHKAP (99% identical), macaque SPHKAP (95% identical), rabbit SPHKAP (77% identical), dog SPHKAP (76% identical), pig SPHKAP (76% identical), guinea pig SPHKAP (76% identical), rat Sphkap (72% identical), mouse Sphkap (70% identical), tropical clawed frog sphkap (43% identical), zebrafish sphkap (38% identical). Paralogues in human: AKAP11 (17% identical), AKAP4 (10% identical), AKAP3 (8% identical).
Diseases named in the same sentence as SPHKAP in open-access papers:
SPHKAP is named in the same sentence as 9 diseases in open-access papers, as found by Europe PMC text mining. Sharing a sentence is not in itself a finding about the gene and the disease. The quoted sentences say what the papers report.
anencephaly (2 papers, 2019 to 2020). A rare neural tube defect during pregnancy, resulting in the absence of a large portion of the brain and skull in the fetus. "A total of 13 DNVs were identified in 8 anencephaly trios by WES, including two loss of function (LoF) variants detected in pLI > 0.9 genes (SPHKAP, c.2629_2633del, and NCOR1, p.Y1907X)." (PMID 31849593, 2019). "However, whole genome sequencing techniques found candidate NTDs loci and genes in chromosomes 2, 7, 10 and 17 (some of which, i.e. WIPI1, SPHKAP and NCOR1, have recently been associated with anencephaly)." (PMID 32448340, 2020). "Missense variants in WIPI1 may play a role in the genetic etiology of anencephaly, and LoF variants in SPHKAP and NCOR1 may also contribute to anencephaly." (PMID 31849593, 2019).
melanoma (2 papers, 2012 to 2018). A malignant, usually aggressive tumor composed of atypical, neoplastic melanocytes. "This gene list also included genes that have roles in a variety of other cancers e.g. DPP6 is down regulated in melanoma, SPHKAP plays a role in the sphingosine phosphorylation pathway that induces tumor progression and invasion." (PMID 22479372, 2012).
Obesity (1 paper, 2025). Accumulation of substantial excess body fat. "As we observe a correlation between SPHKAP variant effects in T2D and high BMI (as a proxy for obesity), we propose here that SPHKAP might play a pleiotropic role in both disorders by the engagement of common signalling pathways in different tissues." (PMID 41372122, 2025).
cancer (5 papers, 2012 to 2018). A tumor composed of atypical neoplastic, often pleomorphic cells that invade other tissues. "ROBO2 is also a candidate tumor suppressor gene; thus far, there is no clear evidence that FGF13, MAST4 and SPHKAP are associated with cancer development." (PMID 29117265, 2017). "LRP1B and ROBO2 are tumor suppressors, but FGF13, MAST4 and SPHKAP have not been associated with cancer development." (PMID 29117265, 2017). "Amongst the novel targets identified in this study the frequent methylation of the promoter of the gene (SPHKAP) encoding sphingosine kinase anchoring protein in AML was of particular interest since SPHKAP was down regulated in both AML patients and cancer cell lines." (PMID 22479372, 2012). "In addition, SPHKAP was down regulated in cancer cell lines investigated, while the expression of DPP6 and ID4 was variable among cancer cell lines." (PMID 22479372, 2012). "The largest FMGS identified in all these cancer stages contained 8 genes (k = 8; RP1, PCDHAC2, TENM3, SPHKAP, ODZ3, ADAMTS18, SCN5A, PKHD1L1) found in SKCM-stage IV." (PMID 27556693, 2016).
tumor (3 papers, 2012 to 2024). "In this research, the ERGS was composed of 8 ERGs (CXCL9, CYP17A1, DRGX, ENTHD1, HAS1, LAIR2, RETN, and SPHKAP), some of which were pivotal to the tumor progression." (PMID 38600248, 2024).
SPHKAP also shares sentences with these, for which no sentence is quoted: diabetes (1 paper); lung adenocarcinoma (1); primary immunodeficiency (1); scoliosis (1).